CD276 (CD276 molecule)
Diseases named in the same sentence as CD276 in open-access papers (continued):
Sharing a sentence is not in itself a finding about the gene and the disease.
tumor (continued). "After lentiviral transduction on day 4 and sorting on day 7, CD276-, F8-FR4-, and Dual-CAR T cells were expanded until day 14, when they were co-incubated for 48 h with Rh4 and JR tumor cells." (PMID 37924157, 2023). "The number of tumor cells with phenotype CD87+CD117+, CD117+Axl+EGF+CD44+, EGF+Axl+, CD117+EGF+, CD276+CD117+, and EGF+Axl− had a tendency to increase." (PMID 36142766, 2022). "The results showed that CD276, CD40, CD274, CD44, and NRP1 expression was exclusively upregulated in cluster 0 (invasive tumor)." (PMID 36685583, 2022). "Further analysis showed that hypoxia-induced immune checkpoints, such as CD276 and NRP1, upregulation in invasive tumor to block infiltration and activation of B cells and CD8+ T cells to change tumor immune microenvironment." (PMID 36685583, 2022). "These highlights the interesting role of CD276 and NRP1 as therapeutic targets of a claudin-low subtype tumor unresponsive to the PD-L1 inhibitor." (PMID 36685583, 2022). "In this review, we present the proliferative role of 15 immune checkpoints, including PD1, PD-L1, FGL1, CD155, CD47, SIRPα, CD276, IDO1, SIGLEC-15, TIM3, Galectin-9, CD70, CD27, 4-1BBL, and HVEM, in tumor progression." (PMID 36358792, 2022). "In cervical cancer, miRNA-199a targets the 3′-untranslated region of CD276 and regulates its expression, and then activates the AKT/mTOR signaling pathway to inhibit tumor proliferation." (PMID 36358792, 2022). "CD276/B7H3, which is located on the cell membrane, is clinically relevant due to its overexpression in tumor tissues and limited expression in normal tissues, coupled with an immunoregulatory role in tumor microenvironment modeling and expansion." (PMID 36550153, 2022). "In solid tumor mice models, blocking of CD276 with mAbs increased CD8+ T and NK cell infiltration, decreased tumor development, and prolonged survivability." (PMID 36338975, 2022). "Recent reports of tumor IHC have implied variable inter- and intratumoral expression of GPC2 and CD276 in NB." (PMID 35852863, 2022). "In these immunostimulatory marker genes, CD276, MICB, NT5E, PVR and ULBP1 had a significantly positive correlation with RRM2 expression in most tumor types." (PMID 35740608, 2022). "PTX3 is closely related to the expression of PD‐1, PD‐L1, CD276, and HAVCR2 in the tumor microenvironment." (PMID 35855654, 2022). "In this regard, we evaluated the expression of SOX2 in blood mononuclear cells expressing tumor markers such as AXL, EGF, CD87, CD90, or CD276." (PMID 36142766, 2022). "Together, these data demonstrated that the BiCisCAR had longer persistence and was less prone to exhaustion in the tumor model with heterogeneous expression of GPC2 and CD276." (PMID 35852863, 2022). "CD276, also named B7-H3, was one of the immune checkpoint molecules, which was upregulated in HNSCC and helped tumor cells evade immunological surveillance." (PMID 35646049, 2022). "In TCGA mRNA data for overall primary tumor samples (n = 1083), mir-29c positively correlated with AR and negatively correlated with CD276/B7H3." (PMID 36550153, 2022). "Further, DSP demonstrated highly consistent expression of both CD276/B7-H3 and TIM-3 across the multiple ROIs within each tumor, indicating low intratumoral heterogeneity." (PMID 33658518, 2021). "Another anti-CD276 ADC, MGC018 also shows antitumor activity across a range of human tumor xenografts." (PMID 33842369, 2021). "Slightly elevated CD276 scores in benigne samples from early-stage BC tumor patients could be caused by a moderate activation of CD276 expression in a few cells surrounding the tumor without showing the typical histology of a BC tumor by microscopy." (PMID 33845814, 2021). "The accumulated data for CD276-CAR NK-92 cells and their resistance to the tumor microenvironment is very promising." (PMID 33925968, 2021). "Another biomarker, B7-H3 (CD276), also increased at the mRNA and protein levels in the tumor regions of combination therapy–treated patients." (PMID 34778231, 2021).
tumor (continued). "PD-1 and CD276 are both members of B7/CD28 family and had similar effects on the tumor growth micro-environment." (PMID 33842369, 2021). "B7-H3, also known as CD276, is highly expressed in multiple tumor tissues and its expression is limited in normal tissues." (PMID 34868903, 2021). "Apart from suppressing T-cell proliferation and activation, experiments have shown that CD276 downregulates several cytokines, such as IFN-γ, TNF-a, and IL-2, while in vitro studies suggest its potential role in tumor invasion and metastasis as well." (PMID 33918733, 2021). "We found that the microenvironment score, matrix score, and immune score were higher, the tumor purity was significantly decreased, and the matrix content was increased in the group with high expression of CD34/CD276." (PMID 34307389, 2021). "The expression of certain immune checkpoints (such as PDCD1LG2, HAVCR2, CD276, and IDO1) also played an important role in the regulation of immune response by inhibiting the activation of anti-tumor immunocytes and inducing immune escape." (PMID 34490033, 2021). "Combination therapy with anti-CD276 antibody and anti-PD1/PD-L1 antibody for tumor treatment is another hot topic of research." (PMID 33842369, 2021). "MGA271 inhibition of CD276 in RCC and bladder cancer in tumor xenograft models resulted in inhibition of tumor growth." (PMID 33842369, 2021). "To verify our guess, we investigated tumor-related immune checkpoints, including CD273, CD274, CTLA-4, and the ones that were newly emerging, LAG-3, TIM-3, TIGIT, CD276, BTLA, and IDO1, between the two subgroups." (PMID 33558879, 2021). "The ssGSEA analysis of tumor samples with high and low expression of CD34/CD276 showed that the tumor samples with high expression of CD34/CD276 had a higher immune score, and ssGSEA was a single sample GSEA algorithm." (PMID 34307389, 2021). "The results showed that PBK knockdown significantly increased the percentage of lysis TW03 cells when the tumor cells were cocultured with CD3/CD28-activated human HLA-A2+ T lymphocytes, and this increase was markedly reversed by the recovery of CD276." (PMID 33431797, 2021). "In this study, we detected high positive expression of CD276 in ACC tissues, including in tumor cells and the tumor vasculature." (PMID 31998416, 2020). "Immune checkpoints such as CD276 and LAG‐3 were upregulated, and higher M2 macrophage infiltration in tumor tissues." (PMID 33033616, 2020). "In conclusion, in this study, we demonstrate for the first time the clinical significance of CD276 expression in ACC cells and the tumor vasculature." (PMID 31998416, 2020). "In the HCC tissues, PD-L1 was mainly expressed in the cellular membrane and cytoplasm of tumor cells in a diffuse manner; CD4/CD8, CD276 and SOCS3 protein were also mainly found in the cytoplasm and membrane of tumor cells." (PMID 32742491, 2020). "Of the genes queried, CD276 (B7-H3) and CD200 had the highest expression in both the tumor samples and the JN-DSRCT-1 cell line." (PMID 32703985, 2020). "CD276, as a costimulatory molecule, is participate in the secretion of IFN-γ during the T cell activation, and also regulates tumor immune microenvironment involving the aggressiveness of various tumors 22-24." (PMID 32742491, 2020). "Gender, age, hormone secretion, laterality, tumor size, T stage, N stage, ENSAT stage, R status, Ki67 index, and all 3 different expression patterns of CD276 were included in the regression model." (PMID 31998416, 2020). "Several receptors have already been explored for this approach, namely CD13, CD276, Extra domains of fibronectin (A, B), Integrin αvβ3, Neuropilin-1, Nucleolin, PDGFRβ, tissue factor, and VEGFR-2, which are overexpressed on tumor vasculature." (PMID 33568892, 2019). "In AML, the trends for CD276, IDO1, and NKG7 all have substantially different intercepts and slopes than seen in the other tumor types." (PMID 29929551, 2018).
tumor (continued). "B7-H3 (B7 homologue 3, CD276) is a member of the B7 immunoregulatory family and promotes tumor progression." (PMID 29069741, 2017). "Recent progresses in tumor immunology identified a series of costimulatory molecules such as B7 homolog 1 (B7-H1, PD-L1, CD80), B7-H2 (CD 86), B7-H3 (CD 276), and B7-H4 (B7x, B7S1)." (PMID 27835582, 2016). "Similarly, CD276, a member of the B7 family, not only hinders the infiltration of CD8+ T cells into the tumor microenvironment, but also promotes T cell exhaustion by downregulating the secretion of key cytokines, such as IFN-γ." (PMID 40672941, 2025). "Beyond its immunomodulatory functions, CD276 also exerts non-immune oncogenic effects by enhancing tumor cell migration, invasion." (PMID 41488652, 2025). "Notably, in a humanized xenograft mouse model, EBVaGC with elevated CD276 levels exhibited resistance to anti-PD1 immunotherapy, while targeting CD276 in combination with PD1 blockade significantly reduced tumor size." (PMID 41419460, 2025). "Ex vivo IVIS imaging of tumor and major organs, including the heart, liver, spleen, lungs, kidneys and brain, further confirmed the specific targeting of CD276 mAb to TNBC, with no detectable off-targeting accumulation in normal organs." (PMID 41462289, 2025). "In preclinical models for treating pediatric rhabdomyosarcoma with FGFR4 and CD276, and B-ALL with CD19/CD20, dual CARs with diverse co-stimulatory domains (CD28 and 4-1BB) showed better persistence and anti-tumor activity than dual CARs with the same co-stimulatory domains." (PMID 40072049, 2025). "Regarding immune checkpoint genes, CD276 and NRP1 are positively correlated with the genes in our model, while TNFSF14 shows a negative correlation with these genes in the tumor immune microenvironment of high-risk patients." (PMID 40299539, 2025). "To investigate correlations between CD276 expression and BLCA patient survival, we first collected 93 tumor tissue specimens from BLCA patients who underwent surgical treatment at the Fourth Medical Center of PLA General Hospital and evaluated CD276 expression using immunohistochemistry (IHC)." (PMID 38561369, 2024). "The CD276 expression is revealed to be significantly higher in tumor tissues compared to that in adjacent non-cancerous tissues (χ2 = 98.86, p<0.001)." (PMID 39319055, 2024). "Overall, CD276 might mediate the reconstruction of TME by influencing various signaling pathways, and promoting tumorigenesis and tumor progression." (PMID 39766794, 2024). "CD276, known for its dual role in the immune system, was found in our study to be highly expressed in tumor samples compared to adjacent non-neoplastic tissue." (PMID 38979413, 2024). "The in vitro observations on CD276 and CD73 were confirmed in in vivo tumor models." (PMID 39308864, 2024). "When considering the potential toxicity and side effects of 8H8_SDIE, it is important to note that CD276 is not exclusively expressed on tumor cells." (PMID 38637557, 2024). "Despite the fact that the CD276 receptor is yet not defined, accumulating evidence indicates that CD276 promotes tumor progression." (PMID 39367484, 2024). "In addition, we examined the expression of CD276 in a commercial tissue microarray containing 63 BLCA and 16 para-tumor tissues via IHC staining." (PMID 38561369, 2024). "Interestingly, we observed marked upregulation of a series of immune checkpoints (e.g., CD86, CD80, HAVCR2 and LGALS9) in most tumor infiltrating myeloid cells, and a unique pattern in TAMs (e.g., NECTIN2, TNFRSF14, CD276 and TNFRSF9)." (PMID 38414027, 2024). "The medium-dose CD276 Dash CAR-T group had no tumor recurrence until the end of the trial (our experiment end on the day 115 after the treatment), and the low-dose Dash CAR-T group had slow tumor growth in some mice on day 91 after administration." (PMID 38978106, 2024).
tumor (continued). "Other immune checkpoints that have played significant roles are CD276, leukocyte immunoglobulin-like receptor subfamily B member 2 (LILRB2), and CD47, which were upregulated in CSCs and led to a weakened or damaged host anti-tumor response." (PMID 39335624, 2024). "Current research shows that CD276 is a member of the negative B7 family, which inhibits T cell activation and plays a negative regulatory role in tumor immunity." (PMID 38581529, 2024). "Additional immune-checkpoints that may also contribute to tumor immune escape have been introduced such as CD47, B7-H3 (CD276), B7-H4 (VTCN1,B7X), CD39 and CD73." (PMID 38439112, 2024). "It has been demonstrated that blocking CD276 with monoclonal antibodies increases the tumor infiltration of CD8+ T cells and NK cells, reduces tumor growth, and prolongs survival in different mouse tumor models." (PMID 39766794, 2024). "Our study suggests that FTSJ1 may regulate the expression of CD276, which partly explains the effect of FTSJ1 on tumor and tumor immunity." (PMID 38339348, 2024). "Thus, the general patterns of regulation: pTERTmut repression of CD8+ and NK cytotoxic cells with or dendritic cells; and relatively high levels of CD276/B7-H3 and CD274/PD-L1 were exhibited by both tumor sample cohorts." (PMID 39717106, 2024). "However, FGFR4.8HTM.BBz-CD276.8HTM.BBz BiCisCAR, which shares the same CD8 HTM and 4-1BB CSD for both FGFR4 and CD276 CAR cassettes, only delayed tumor progression compared to mock T-cells in an RH30 orthotopic xenograft model." (PMID 39043633, 2024). "Immunohistochemical assays revealed that CD276 was present in 78.20% of tumor specimens, as opposed to 17.29% of normal tissue samples." (PMID 39319055, 2024). "The immune analysis results show that high-expression of DLD may reduce T cell-mediated anti-tumor immunity by regulating immune infiltration of CD8 + T cells and positively regulating immune checkpoints LAG3 and CD276." (PMID 38581529, 2024). "Therefore, by utilizing gene editing technology to disrupt genes like PD-1 and CD276 in CAR-T cells, researchers inhibit the tumor microenvironment and enhance the therapeutic efficacy of CAR-T cells." (PMID 39136031, 2024). "In this study, 95% of NB samples had high expression of GPC2 and CD276, and CT3 and MGB7H3‐LH were confirmed to be effective CAR constructs for recognizing GPC2‐ and CD276‐expressing tumor cells using multimodal single‐cell analysis methods and cytotoxicity assays." (PMID 38090056, 2023). "Comprehensive analysis of the NSCLC tumor ecosystem identified B7 homolog 3 protein (B7H3, also known as CD276) as a type I transmembrane protein that is broadly overexpressed by malignant cells and tumor-associated cells, but with restricted expression in normal tissues." (PMID 37848956, 2023). "B7-H3 (also known as CD276), a member of the B7 family of immune checkpoint proteins, is highly expressed in cancer cells and activated tumor-infiltrating immune cells, and helps cancer cells to evade the surveillance of cytotoxic T-cells and natural killer cells." (PMID 36859240, 2023). "This might theoretically also reduce homing and decrease the probability by CD276-CAR T cells to encounter the target, protecting RD tumor cells during the first week of experiment." (PMID 37924157, 2023). "Adjusting the labeling conditions to ensure similar fluorophore amounts on all three CD276 antibodies, we injected 50 μg (~2 mg/kg) of each antibody-fluorophore conjugate (AFC) into tumor-bearing mice and performed fluorescence imaging in vivo and ex vivo after 72 h." (PMID 38019654, 2023). "We hypothesize that intrinsic expression of CTLA-4, PDCD1 (PD1), CD274 (PD-L1), PDCD1LG2 (PD-L2), CD276 (B7-H3), JAK2, and FoXO1 in neoplastic cells depends on BC immunophenotype, stem cell properties, and tumor microenvironment." (PMID 36901916, 2023).
tumor (continued). "The B7 immune checkpoint superfamily includes B7-1 (CD80), B7-2 (CD86), B7-H1 (PD-L1, CD274), PD-L2 (PDCD1LG2), B7-H3 (CD276), B7-H4 (B7-x, VTCN1), and the inducible costimulator ligand (L-ICOS, CD275), which act as ligands on the surface of tumor cells or antigen-presenting cells." (PMID 36983005, 2023). "However, the B7-H3/CD276 immune checkpoint protein is highly expressed in mPCa with high androgen receptor activity, and DSP technology has potential in assessing tumor heterogeneity and identifying immune components in metastases." (PMID 37744276, 2023). "In vivo, CD276.V-CAR T cells successfully eradicated Rh4-derived tumors at week 2 of treatment with 100% efficiency whereby in 5/5 mice the tumor did not relapse." (PMID 37924157, 2023). "In addition, we compared significant immune checkpoints between “stiff tumor” and “soft tumor” and observed the expression of CTLA4, CD276 and TNFRSF25 was higher in “stiff tumor”, while the expression of CD47 was higher in “soft tumor”." (PMID 37179366, 2023). "CD276 was previously reported with high expression in CRC tissue and may contribute to the tumor evasion of T-cell mediated responses and has been already proposed as a target for immunotherapy." (PMID 37228491, 2023). "We obtained tumor immune cell infiltration results by utilizing the TIMER2, CIBERSOFT and TISDB databases, and found that CD8+ T cells and B cells were negatively correlated with the expression of CD276 in most types of cancer." (PMID 36717836, 2023). "After co-incubation with tumor cells, the CD28 group showed a decreased CD39 expression for F8-FR4.V and Dual.V CAR T cells (16% ± 1% for both), while CD276.V-CARs remained at higher levels of 22% ± 5% when co-incubated with Rh4 and of 21% ± 5% when co-incubated with JR." (PMID 37924157, 2023). "Additionally, the analysis of the CGGA and TCGA databases also showed that CDCA7 was closely related to several tumor-related suppressors, including CD80, CD276, CD28, PDCD1LG2, and TNFSF4, which contribute to tumor development via multiple mechanisms." (PMID 37510310, 2023). "Therefore, Liu and colleagues conjugated photosensitizer IRDye700 with the Fab fragment of an anti-CD276 antibody to combine antiangiogenic therapy and PDT with PD-1/PD-L1 blockade to treat primary tumors and ablation of tumor metastases." (PMID 36119019, 2022). "B7 homolog 3 protein (B7-H3, also known as CD276) is a member of the B7 family overexpressed in tumor tissues, including non-small cell lung cancer (NSCLC), while showing limited expression in normal tissues, becoming an attractive and promising target for cancer immunotherapy." (PMID 36555714, 2022). "The CD24-expressing tumor stem cells did not home to the metastases in the lymph nodes, whereas CD276-expressing cells were found in the metastases." (PMID 35563359, 2022). "B7.H3, also known as CD276, promotes anti-tumor immune response by activating T and NK cells." (PMID 35651606, 2022). "Recently, it has been demonstrated that hybrid E/M cells induce the formation of a tumor-promoting microenvironment through the upregulation of potent immunosuppressive proteins, including PD-L1, CD73 (5′-NT), CD276 (B7-H3), CSF1 (M-CSF), SPP1, galectin-3, MASP1, and SDF1 (CXCL12)." (PMID 36467417, 2022). "Gray-scale analysis by ImageJ software also showed that the expression level of normalized fucosylated ITGB1 and CD276 in tumor tissues was significantly higher than those in normal tissues." (PMID 35752862, 2022). "Intriguingly, together with CD274 (PD-L1), CD276 (B7-H3) and VEGFA were both highly expressed in the cold tumours, which could be further investigated as novel immunotherapy targets for such patients." (PMID 36267973, 2022). "Importantly, CD276 blockade significantly inhibited lymph node metastasis of HNSCC, enhancing anti-tumor immunity." (PMID 35982868, 2022).